VPS72 (vacuolar protein sorting 72 homolog)
Description:
Deposition-and-exchange histone chaperone specific for H2AZ1, specifically chaperones H2AZ1 and deposits it into nucleosomes. As component of the SRCAP complex, mediates the ATP-dependent exchange of histone H2AZ1/H2B dimers for nucleosomal H2A/H2B, leading to transcriptional regulation of selected genes by chromatin remodeling.
Synonyms: TCFL1; YL1; YL-1; Swc2
Tractability: Small molecule: a structure with a bound ligand is known. PROTAC: UniProt records ubiquitination sites on it; ubiquitination databases record sites on it; its protein half-life has been measured.
Gene: Protein-coding gene on chromosome 1 (151,176,304 to 151,195,321, reverse strand). Ensembl gene ENSG00000163159.
Subcellular location: Nucleus
Subcellular location (Human Protein Atlas): Nuclear speckles
Pathways (Reactome):
Chromatin organization: HATs acetylate histones
Gene Ontology:
Molecular function: histone binding; histone chaperone activity; protein binding
Biological process: positive regulation of double-strand break repair via homologous recombination; regulation of cell cycle; transcription initiation-coupled chromatin remodeling; chromatin remodeling; negative regulation of transcription by RNA polymerase II; positive regulation of DNA-templated transcription; regulation of apoptotic process; regulation of DNA-templated transcription; regulation of double-strand break repair
Cellular component: NuA4 histone acetyltransferase complex; nuclear speck; nucleosome; protein-containing complex; nucleoplasm; nucleus
Genetic constraint (gnomAD): Loss-of-function variants: 27 observed, 40.76 expected, observed/expected ratio (o/e) 0.66, 90% interval 0.49 to 0.91. The upper end of that interval is the gene's LOEUF score, 0.91, which puts it in group 3 of 6, group 1 being the genes least tolerant of losing a copy. Missense variants: 360 observed, 503.67 expected, observed/expected ratio (o/e) 0.71, 90% interval 0.65 to 0.78. Synonymous variants: 173 observed, 196.99 expected, observed/expected ratio (o/e) 0.88, 90% interval 0.77 to 1.
Homologues: Orthologues: chimpanzee VPS72 (99% identical), macaque VPS72 (99% identical), dog VPS72 (98% identical), pig VPS72 (97% identical), mouse Vps72 (97% identical), rat Vps72 (97% identical), guinea pig VPS72 (96% identical), rabbit VPS72 (88% identical), zebrafish vps72b (60% identical), zebrafish vps72a (60% identical), Drosophila melanogaster YL-1 (35% identical), Caenorhabditis elegans C17E4.6 (30% identical).
Diseases named in the same sentence as VPS72 in open-access papers:
VPS72 is named in the same sentence as 8 diseases in open-access papers, as found by Europe PMC text mining. Sharing a sentence is not in itself a finding about the gene and the disease. The quoted sentences say what the papers report.
hepatocellular carcinoma (4 papers, 2022 to 2025). A malignant tumor that arises from hepatocytes. "Upregulated VPS72 expression in HuH7 cells confirmed by western blot and RT-qPCR also suggests that VPS72 expression is intimately implicated in the development of hepatocellular carcinoma." (PMID 35383533, 2022). "Together, these experiments results indicate that VPS72 is highly expressed in the hepatocellular carcinoma tissues and cell lines and high VPS72 expression is implicated in poor prognosis." (PMID 35383533, 2022). "Results indicated that VPS72 was highly expressed in hepatocellular carcinoma tissues and cell lines and was associated with poor prognosis." (PMID 35383533, 2022). "In our study, by biological information analysis, we found that VPS72 was highly expressed in hepatocellular carcinoma tissues and was associated with poor prognosis." (PMID 35383533, 2022). "In this study, the expression of VPS72 in hepatocellular carcinoma tissues and overall survival were analyzed using GEPIA2 database." (PMID 35383533, 2022). "In this study, both VPS72 and KAT5 were shown to be highly expressed in hepatocellular carcinoma cells, and their high expression was associated with poor prognosis." (PMID 35383533, 2022). "The functions of VPS72 on malignant biological properties of hepatocellular carcinoma cells were explored in the subsequent experiments." (PMID 35383533, 2022). "Efforts have been made in this paper and it was concluded that VPS72 knockdown inhibited the proliferation, invasion and migration of hepatocellular carcinoma cells." (PMID 35383533, 2022). "Firstly, VPS72 expression in hepatocellular carcinoma tissues and the prognostic correlation were analyzed by GEPIA2 database." (PMID 35383533, 2022). "Western blotting and RT-qPCR assays were used to evaluate VPS72 expression in several hepatocellular carcinoma cell lines." (PMID 35383533, 2022). "In our study, upregulated KAT5 expression in HuH7 cells and the targeting binding of KAT5 and VPS72 identified by Co-IP detection revealed the fact that KAT5 may bind to VPS72 to affect the progression of hepatocellular carcinoma." (PMID 35383533, 2022). "In this article, what we explore is the role of VPS72 in hepatocellular carcinoma." (PMID 35383533, 2022). "Subsequently, KAT5 was overexpressed to explore whether VPS72 could regulate the progression of hepatocellular carcinoma by binding to KAT5." (PMID 35383533, 2022). "For the sake of figuring out whether VPS72 has an effect on the proliferative ability of hepatocellular carcinoma cells, HuH7 cells were transfected with sh-VPS72#1 and sh-VPS72#2 to silence VPS72 expression." (PMID 35383533, 2022). "Based on initial evidence linking VPS72 to hepatocellular carcinoma progression, we examined TCGA Liver Hepatocellular Carcinoma (LIHC) patient data to explore the correlation between VPS72 copy number, expression levels, and patient survival outcomes." (PMID 40305746, 2025). "Our research shows that vacuolar protein sortings (VPSs) play an essential role in the occurrence and development of hepatocellular carcinoma (HCC), especially VPS72 can be used as a potential target for treatment and prognosis biomarker of HCC." (PMID 37249275, 2023). "Similarly, POLR1B knockdown induces lung cancer cell apoptosis, VPS72 knockdown inhibits the proliferation, invasion, and migration of hepatocellular carcinoma (HCC) cells, and UBTF silencing suppresses melanoma cell proliferation." (PMID 37444571, 2023). "The potential mechanism between VPS72 and KAT5 in the progression hepatocellular carcinoma was further investigated." (PMID 35383533, 2022). "Collectively, it is speculated that VPS72 may bind to KAT5 to promote proliferation, invasion and migration of hepatocellular carcinoma cells by regulating PI3K/AKT signaling pathway." (PMID 35383533, 2022).
hepatocellular carcinoma (continued). "This study only analyzed VPS72 expression and its correlation with disease progression in hepatocellular carcinoma tissues using GEPIA2 database, which have not been validated in clinical hepatocellular carcinoma tissues collected from patients." (PMID 35383533, 2022). "Additionally, we only discussed the effects and regulatory mechanism of VPS72 and KAT5 in hepatocellular carcinoma cells." (PMID 35383533, 2022).
prostate carcinoma (3 papers, 2023 to 2024). A carcinoma that arises from epithelial cells of the prostate gland. "Biased towards African-specific drivers (63 versus 9 shared), many are novel to prostate cancer (18/63), including several putative therapeutic targets (CHD7, DPF3, POLR1B, SETD1B, UBTF, and VPS72)." (PMID 37444571, 2023).
liver cancer (2 papers, 2023 to 2025). An epithelial or non-epithelial malignant neoplasm that arises from the liver. "Notably, tumors with VPS72 copy number gain (>median expression) and ATF3 loss (<median expression) exhibited heightened mTORC1 activation, suggesting that mTORC1 signaling is a downstream target of VPS72 amplification in liver cancer." (PMID 40305746, 2025). "Therefore, VPS72 may influence the efficacy of immunotherapy in patients with liver cancer by affecting immune cell infiltration, but more research is required." (PMID 37249275, 2023). "To further elucidate the relationship between VPS72 and ATF3 expression, as well as their connection to mTORC1 activity in liver cancer, we conducted data mining of liver cancer expression datasets." (PMID 40305746, 2025). "Analysis of the TCGA LIHC database revealed a negative correlation between VPS72 and ATF3 expression, indicating that VPS72 amplification may downregulate ATF3 in liver cancer." (PMID 40305746, 2025).
breast carcinoma (1 paper, 2025). "Given the prevalent alteration in breast cancer, this prompts further research on the possibility of utilizing VPS72 expression as a prognostic indicator in breast cancer." (PMID 41278204, 2025).
cancer (3 papers, 2023 to 2025). A tumor composed of atypical neoplastic, often pleomorphic cells that invade other tissues. "Future studies should aim to elucidate additional VPS72‐regulated pathways and explore its potential as a therapeutic target across different cancer types." (PMID 40305746, 2025). "While the oncogenic role of H2A.Z—a histone variant critical for chromatin dynamics—has been increasingly recognized in cancer, its chaperone VPS72 has remained largely understudied." (PMID 40305746, 2025). "YL1, encoded by the vacuolar protein sorting 72 homologs (VPS72) gene, is a subunit shared by the SRCAP and TIP60/p400 complex and is frequently amplified in many cancers, including breast and melanoma." (PMID 41278204, 2025). "By repressing ATF3, VPS72 drives lipid biosynthesis and tumor progression, highlighting a novel mechanism of metabolic regulation in cancer." (PMID 40305746, 2025). "By analyzing multiple GEO chip data, the overexpressed VPS72 in HCC tissues was examined, revealing that VPS72 was overexpressed in cancer tissues of HCC patients with multiple data sets in the ONCOMINE database." (PMID 37249275, 2023). "This suggests that NASH‐driven HCC may rely less on VPS72 amplification to initiate cancer development, indicating a potential divergence in the underlying oncogenic pathways." (PMID 40305746, 2025). "Our findings elucidate the complex role of VPS72 as an epigenetic regulator of lipid metabolism in HCC and establish a critical link between the development of cancer and lipid homeostasis." (PMID 40305746, 2025).
tumor (2 papers, 2023 to 2025). "VPS72 expression was markedly higher in tumor tissues compared to normal controls, and survival analysis revealed a strong association between elevated VPS72 expression and reduced overall survival." (PMID 40305746, 2025). "The result indicates that compared with the control group, VPS72 knockdown significantly represses tumor growth in vivo." (PMID 40305746, 2025). "Consistently, IHC assays confirmed decreased expression of FASN, ACLY, and SCD in tumor tissues derived from VPS72 knockdown cells." (PMID 40305746, 2025). "Univariate and multivariate Cox analyses were employed to assess the prognostic value of VPS72 as an independent factor, and the correlation between VPS72 and the tumor immune microenvironment was also analyzed." (PMID 37249275, 2023). "The fold change in Wurmbach liver is 2.605; based on the Wambach data set, the higher VPS72 expression was found in higher tumor grades, hepatitis C virus (HCV) positive, patients with satellites, and vascular invasion." (PMID 37249275, 2023). "Through Gene Set Enrichment Analysis (GSEA) enrichment analysis, we found that multiple signal pathways affecting tumor progression were affected by VPS72." (PMID 37249275, 2023).
VPS72 also shares sentences with these, for which no sentence is quoted: melanoma (2 papers); lung carcinoma (1).